IL6 (interleukin 6)
Diseases named in the same sentence as IL6 in open-access papers (continued):
Sharing a sentence is not in itself a finding about the gene and the disease.
tumor (continued). "Exercise mediates NK cell mobilization and trafficking through IL-6-dependent and adrenaline-dependent pathways, thereby limiting tumor growth." (PMID 39064705, 2024). "The next step of tumorigenesis is the proliferation and growth of tumor cells which is mainly induced by various cytokines(e.g.IL-1, IL-6, TNF-α), which is concluded in the process of promotion." (PMID 39493763, 2024). "Interleukin-6 is a pro-inflammatory cytokine produced in the tumor microenvironment by immune, stromal, and tumor cells." (PMID 39596207, 2024). "Similar results were observed for Tumor Necrosis Factor alpha (TNF-α) and Interleukine-6 (IL-6) within tumor, 2 cytokine genes coding for pro-inflammatory." (PMID 38426110, 2024). "IL-6-activated STAT3 in turn promotes tumor cell survival by inducing the expression of Bcl-2, survivin, and X-linked inhibitor of apoptosis protein (XIAP), the overexpression of which is related to increased chemoresistance." (PMID 38520006, 2024). "For example, TAMs can induce tumor cell autophagy by producing inflammatory factors such as IL-6 (interleukin-6) and IL-8 (interleukin-8)." (PMID 38675475, 2024). "Circulating IL-6 has been defined as a prognostic marker in various cancer types, implying significance in tumor biology." (PMID 38689325, 2024). "Tumor-bearing mice exhibited interleukin-6 (IL-6)-mediated peripheral inflammation, which coincided with disrupting metabolism and sleep by altering specific neuronal populations." (PMID 39268034, 2024). "Interleukin-6 (IL-6) is a common pluripotent cytokine that is highly expressed in the tumor microenvironment." (PMID 38274367, 2024). "M1 macrophages produce various pro-inflammatory mediators, including TNF-α, IL-1, IL-6, active nitrogen and oxygen intermediates, which exhibit potent bactericidal and tumor-killing activities, give aid to infection clearance and trigger inflammation." (PMID 38715602, 2024). "The therapeutic role of ginsenoside Rg1 can be explored for inflammatory, immune, and tumor diseases by regulating the IL-6/STAT3-TYRO3-telomere network." (PMID 38431573, 2024). "IL-6 can initiate tumorigenesis and/or tumor progression by inhibiting dendritic cell differentiation, inducing immune tolerance in the early stages of tumor development, and facilitating metastasis." (PMID 38612423, 2024). "AML-MSCs have been found to have high levels of VEGFA and IL-6, which contribute to tumour-supportive angiogenesis." (PMID 39200142, 2024). "The strong pro-tumorigenic effects of IL-6 come from its role in bone metabolism, tumor cell proliferation and survival, angiogenesis, and inflammatory responses." (PMID 38791037, 2024). "IL-6 and G-CSF from stromal or tumor sources can activate STAT3 signaling, resulting in an increase in suppressive immune effects of PMN-MDSCs by enhancing C/EBPβ expression and inhibiting IRF8 expression." (PMID 38689325, 2024). "IL-6: Similarly, the involvement of IL-6 in bone metastasis is evident through its capacity to affect the settlement of tumor cells in bone via several signaling cascades, including JAK/STAT and MAPK pathways." (PMID 39125732, 2024). "Collectively, these viral proteins drive the production of growth factors and cytokines such as VEGF, PDGF and IL-6 to promote angiogenesis and tumor growth." (PMID 39386738, 2024). "Altogether, the transdifferentiation from cDC2s to CD14+ cDC2s is dominantly driven by M-CSF and IL-6, secreted by tumor cells and present in serum from cancer patients." (PMID 38242119, 2024). "We further tested the expression of IL6 in tumors treated with diABZI, and the ELISA results showed that diABZI treatment did significantly increase the release of IL6 in the tumor microenvironment." (PMID 38615022, 2024). "Conversely, inhibitory tumor‐type CAFs can negatively regulate tumor T cell responses by secreting immunosuppressive factors such as interleukin‐6 (IL‐6) and tumor necrosis factor‐alpha, or by promoting the recruitment of myeloid‐derived suppressor cells." (PMID 39415846, 2024).
tumor (continued). "Detailed phenotypic profiling showed that TREM1 myeloid cells were enriched for IL1A, OSM, and IL6 expression compared to other myeloid populations, further supporting the association between BIT tumor epithelium and TREM1 myeloid-derived IL1A and OSM." (PMID 39289380, 2024). "Nevertheless, how autophagy-inhibited tumor cells facilitate the secretion of IL-6 and the source of iron in CAFs remains to be further investigated." (PMID 38649701, 2024). "They usually play an immunosuppressive role; however, capability of these cells of extracellular matrix (ECM) remodeling and the secretion of anti-inflammatory cytokines (TGFb, IL6) is hijacked by tumor cells." (PMID 38786032, 2024). "Results: at the time of tumor diagnosis, high inflammatory biomarkers (c-reactive protein (CRP), interleukin-6 (IL-6)) and albumin serum levels were associated with impaired OS in PDAC patients, but not in patients with oAC." (PMID 38539528, 2024). "Following tumor inoculation, tissue IL‐6 mRNA levels were on average higher in skeletal (136.70%, p = 0.065) and cardiac (142.60%, p = 0.073) muscle, respectively." (PMID 39294861, 2024). "IHC staining of tumor tissue and qPCR of blood mice levels of IL-6 were markedly inhibited in stable knockdown IL-6 cells." (PMID 38993553, 2024). "Exercise training also increased IL‐6 and IL‐15 levels in the blood and altered the expression of apoptosis‐related proteins in tumor tissue, with the combined treatment group showing even more significant changes." (PMID 38234174, 2024). "IL-6’s involvement in cancer extends beyond inflammation, since the IL-6 serves as “fuels” to tumor growth, promoting angiogenesis, and facilitating metastasis." (PMID 39015561, 2024). "SAADKO tumor-bearing mice displayed lower concentrations of IL-1β (p = 0.030), IL-6 (p = 0.003), and IL-10 (p = 0.014) compared to WT tumor-bearing mice." (PMID 39336082, 2024). "MSC-Exo can also promote tumour metastasis and invasion by delivering cytokines (such as IL-6) to target cells." (PMID 38302430, 2024). "Macrophages are tumor-promoting cells acting by secreting cytokines, such as IL-6, IL-1β, and TNF-α." (PMID 39064019, 2024). "Of note, with tocilizumab treatment the pleiotropic effects of IL-6, which include pro- and anti-tumor effects, have to be considered." (PMID 38242119, 2024). "This led to the concept that in tumor cells, IL-6 activates Stat3, which in turn leads to the release of IL-6." (PMID 39000275, 2024). "To date, studies for IL-6-mediated STAT3 activation within the tumor microenvironment mainly focus on tumor cells, T cells, and DC cells." (PMID 38274367, 2024). "Regarding the expression levels of proinflammatory cytokines in tumor tissues, the relative IHC scores of IL-17 and IL-6 were clearly increased after P. intermedia infection compared with those in the control group." (PMID 38644421, 2024). "Possibly, soluble factors, such as IL-6 and IL-8, produced upon activation of the Fas/Fas-L interaction, are responsible for circulating neutrophils and their infiltration into the tumor." (PMID 38339353, 2024). "Peritumoral fibroblasts significantly influence tumor cells, promoting enhanced proliferation, migration, and invasion, partly through interleukin-6 (IL-6)-mediated signaling pathways." (PMID 39001498, 2024). "The IL-6/STAT3/xCT axis functioned as a novel mechanism that promoted tumor development, and thus, IL-6 can be used as a target for tumor treatment and prevention." (PMID 39099925, 2024). "The immunoreactivity scoring system (IRS) showed a significant difference in IL-6 expression between tumor and stromal cells, with higher expression levels observed in stromal cells (P<0.05)." (PMID 38510850, 2024). "Increasing evidence suggests that cytokines, including IL-8 and IL-6, can alter the phenotype of neutrophils and thereby produce tumor-promoting effects." (PMID 39409083, 2024).
tumor (continued). "A variety of inflammatory mediators can induce MDSC expansion and recruitment to the TME, including tumor-derived IL-6, IL-8, IL-10, CSF-1, CCL2, CXCL2, PGE2, and TGF-β." (PMID 38254796, 2024). "As a versatile cytokine, IL-6 has broad and robust effects on tumor-promoting inflammation, the EMT process, and metastasis." (PMID 38459511, 2024). "Our study emphasized the role of IL6high CAF on tumor cells for elevating level of various cytokine genes including IL6, IL32, IL33, CXCL1, CXCL3 and CXCL8, and oncogenic pathways, such as the Wnt and VEGF signaling pathways." (PMID 38892065, 2024). "JAK2/STAT3 is a classical IL-6 signaling pathway that can promote inflammation and tumor progression." (PMID 38424624, 2024). "Research has indicated that tumor cells secrete cytokines, such as granulocyte colony-stimulating factor (G-CSF), interleukin-1β (IL-1β), interleukin-6 (IL-6), and tumor necrosis factor (TNF), which are believed to extend the lifespan of neutrophils." (PMID 39143953, 2024). "CAFs have been shown to support tumor cells through exosomal transfer and the paracrine signaling mediated by NF-κB and cytokines such as IL-6, thereby activating the downstream JAK/STAT3, mechanistic target of rapamycin (mTOR), and SHH pathways." (PMID 38318525, 2024). "The IL family, such as IL-6, IL-4, and IL-10, can polarize TAMs toward the M2 type with the pro-tumor effect and diminished antigen-presenting ability, which can decrease T-cell infiltration and promote the establishment of an immunosuppressive TME." (PMID 39497925, 2024). "Tocilizumab has been investigated for its role in reducing bone metastases by inhibiting the pro-tumor effects of IL-6." (PMID 39125732, 2024). "Tumor patients who showed higher concentrations of IL-6 in their blood in clinical had suppression of CD8+ T cells proliferation and cytokine generation, and they had higher adverse clinical outcomes." (PMID 39372416, 2024). "IL-6 also regulates MMPs, with increased MMP expression leading to elevated IL-6 levels, creating a positive feedback loop that exacerbates tumor development and metastasis." (PMID 39872848, 2024). "Macrophages internalize p-MET, leading to increased levels of IL-1β and IL-6 mRNA and elevated IL-1α secretion, which fosters tumor growth." (PMID 39726601, 2024). "We conducted tumor treatment-related immune cell and Th1/Th2 subset detection in the patient, comparing the concentrations of 6 cytokines (IL-2, IL-4, IL-6, IL-10, TNF-α, and TNF-γ) and various immune cells in peripheral blood before and after treatment." (PMID 39871939, 2024). "Among these cytokines, IL-6 is a major cytokine present in the tumor microenvironment and is overexpressed in almost all types of tumors." (PMID 38533503, 2024). "Activated through the TNFAIP3/NF-κB signaling pathway, fibroblasts induce the formation of a premetastatic niche and promote tumor growth by secreting proinflammatory cytokines, such as IL-6 and IL-8." (PMID 38473285, 2024). "The cytokine interleukin-6 (IL-6) is very often present at the tumor–normal tissue interface as it is secreted by cancer cells but also by other cellular components of the tumor microenvironment such as endothelial cells or tumor-infiltrating macrophages." (PMID 38473317, 2024). "In contrast to TAMs exhibiting an M2, pro-tumoral phenotype, M1 TAMs are classically associated with playing an anti-tumor role by secreting factors known to inhibit tumor growth, such as TNF-α, IL-1β, IL-6, IL-8, IL-12, and IL-23." (PMID 38893093, 2024). "IL-6 is one of the most important cytokines in the tumor microenvironment, and many studies have proved that IL-6 is involved in cancer cell growth and metastasis." (PMID 38612999, 2024). "Targeting O‐glycosylation by itraconazole successfully suppressed serum IL‐6 levels, upregulated tumor infiltrating CTLs, and downregulated MRC1+ TAMs in vivo." (PMID 37452653, 2024).
tumor (continued). "M1 macrophages stimulate antitumor responses by producing proinflammatory cytokines such as IL-6, IL-12, IL-23, etc., whereas M2 macrophages promote tumor immune evasion by recruiting Tregs and secreting immunosuppressive cytokines like IL-10 and TGF-β." (PMID 39691393, 2024). "IL6 has been shown to enforce proliferation and anti-apoptotic effects in tumour cells to promote tumour progression." (PMID 38468450, 2024). "Subsequently, IL-1-activated EGCs produce IL-6, and promote the tumour-infiltrating monocytes differentiation into pro-tumorigenic SPP1+ TAMs." (PMID 38957473, 2024). "Cytokines including TGF-β, IL-6, and IL-10 promote tumor development by inhibiting efficient immune surveillance." (PMID 39767682, 2024). "It has been indicated that these cytokines promote the invasive properties and proliferation of BCSCs, with IL‐6 facilitating the homing of MSCs to tumor sites in mouse xenograft models." (PMID 39070181, 2024). "IL-6 exhibits both pro- and anti-inflammatory actions contributing significantly to tumor development." (PMID 38799159, 2024). "Surprisingly, several pro-tumour pathways such as TGF-β signaling, ECM remodelling, and IL-6 signaling were associated with CD56dim NK cell abundance, suggesting these pathways suppress the functions of this NK subset." (PMID 39877370, 2024). "Activation of the IL-6/gp130/STAT3 pathway is closely associated with the proliferation, infiltration, and metastasis of tumour cells, ultimately leading to tumour progression." (PMID 38504172, 2024). "In IL-6 knockout mice, tumor growth and formation were downregulated, and proliferation markers and MMP-9 were reduce." (PMID 38438872, 2024). "In tumor cells, IL-6-induced activation of Stat3 was increased or maintained by activation of the epidermal growth factor receptor (EGFR)." (PMID 39000275, 2024). "The PPAR-γ/NF-κB axis is the upstream signal pathway of AQP3-mediated M2 macrophage polarization, while IL-6 is the key downstream molecule of AQP3-mediated tumor progression." (PMID 39060229, 2024). "Cancer-associated stroma produces and releases diverse proteins, including IL-6, that promote tumor development and invasion." (PMID 38519574, 2024). "It is critical to understand how cytokines such as IL-1β and IL-6 regulate the transcription of inflammatory genes in the tumor microenvironment and how these cytokines interact with immune cells in that microenvironment." (PMID 39526199, 2024). "Concurrently, the lysis of tumor cells liberates additional inflammatory cytokines such as IL-18 and IL-6." (PMID 39521987, 2024). "IL-6 plays an important role in the pathogenesis and progression of malignant tumors by promoting tumor growth through inhibiting apoptosis and induces tumor angiogenesis." (PMID 38952546, 2024). "It has been shown that the levels of interleukin family 1 and IL-6 are significantly higher in tumor-lesioned tissue compared to healthy tissue." (PMID 38534756, 2024). "IL-6 is responsible for inducing and triggering the release of a large number of pro-inflammatory cytokines in the tumor." (PMID 39770330, 2024). "ECs also regulate tumor progression and metastasis by secreting angiocrine factors, such as IL-6, TGFβ, and VEGF." (PMID 39085965, 2024). "TAMs support tumor resistance by regulating drug metabolism and/or secreting cytokines such as IL-6 in several cancer types." (PMID 38397187, 2024). "The hemocytes that recognize the tumor cells by the binding of Eiger are recruited to the FB while secreting Upd3/IL-6." (PMID 39684820, 2024). "Tumor-derived IL-6 stimulates the STAT3 pathway in CAFs, sustaining the CSC-like characteristics of tumor cells by prompting CAFs to release MMPs." (PMID 39092186, 2024). "Several preclinical studies have shown significantly improved tumor control and survival with combination IL-6 blockade (anti-IL6 or anti-IL-6R) and ICI compared with ICI alone, which was postulated to be due to improved Th1/Th17 skewing." (PMID 39403935, 2024).
tumor (continued). "For tumor cells, IL‐6 can drive the activation of STAT3, which can promote tumor initiation and progression, resist apoptosis and promote metastasis." (PMID 39235042, 2024). "Factors secreted upon BMSC: tumor cell contact, such as IL-6 in particular, play a pivotal role in MM proliferation, survival, and drug resistance." (PMID 39160158, 2024). "In BC, tocilizumab attenuated the MCT-1/IL-6/IL-6R signaling between tumor cells and TAMs, inhibiting stemness." (PMID 39286635, 2024). "Yu Han Huang etc. proved that IL6 induces vascular endothelial growth factor-C expression in lymphatic endothelial cells, as the effort to understand the underlying mechanism may help in developing novel therapeutic strategies to reduce lymphangiogenesis and tumor metastasis." (PMID 38893732, 2024). "We found that levels of serum IL-6 and the traditional tumor marker CEA were significantly higher in the AIS group compared to those in the BPN/HC group (p < 0.05)." (PMID 38529301, 2024). "We found that the expression level of the proinflammatory cytokine, interleukin 6 (IL6), was significantly elevated in the tumor microenvironment relative to healthy colon tissues." (PMID 39872866, 2024). "Thirdly, breach of the internal elastic lamina of vessels by direct invasion by the tumour cells, subsequent IL-6-mediated inflammation and damage to the arterial wall by excess matrix metalloproteinases leading to subsequent aneurysm formation." (PMID 39283559, 2024). "Considering our findings, overactivated mTORC1 likely facilitates the expression of IL-6 through upregulation of ERO1α, thus promoting cell proliferation and tumor growth in the TSC." (PMID 38610018, 2024). "iCAFs are promoted by fibroblast activation protein (FAP) and STAT3 activation, resulting in secretion of CCL2 and IL-6, significant for promoting MDSCs infiltration into the tumour microenvironment and supporting the growth of malignant cells." (PMID 38920685, 2024). "Serum IL6 is also correlated with tumor burden and is suggested as a tool for monitoring treatment outcomes." (PMID 38672199, 2024). "Such infiltration triggers the activation of myeloid cells that produce IL-23, which boosts tumor-promoting cytokines such as IL-17 and IL-6." (PMID 39456655, 2024). "We showed that fibroblasts activated through tumor-bearing derived EVs showed upregulated expression levels of multiple inflammatory cytokines, such as IL-1β, IL-6, IL-8, TNF-α, and TGF-β, in a time-dependent manner." (PMID 39056778, 2024). "Tumor-related proinflammatory cytokine secretion is one of the main mechanisms underlying CACS, in particular interleukin-1 (IL-1), interleukin-6 (IL-6), tumor necrosis factor alpha (TNF-α), and C-reactive protein (CRP)." (PMID 38822976, 2024). "The upregulation of tumor suppressors miR-30C, and miR-107 and the downregulation of oncogenic factors like miR-25, IL-6 and C-Myc aligns with established targets for anticancer therapy, suggesting potential clinical relevance." (PMID 39209915, 2024). "Recent studies have emphasized the role of pro-inflammatory cytokines, such as TNF-α and IL-6, in promoting immune system-mediated tumor clearance." (PMID 38252337, 2024). "Tumor-associated microglia are drawn to the cancer site by chemokines such as CCL2, and help the tumor to expand and invade by secreting cytokines and growth factors such as IL-6, TGF-β, and VEGF." (PMID 38523646, 2024). "For example, the release of the proinflammatory cytokines TNF-ɑ, NFkB and IL-6 by TAMs induces PD-L1 expression in tumor cells via the NF-kB and STAT3 signaling pathways." (PMID 39516356, 2024). "In the tumor tissue of the TH animals, high expression of Nfkb, Il1b, and Il6 was observed, accompanied by high Tgfb and Il10 expression in the peritumoral area." (PMID 39063041, 2024).